SMC5 (structural maintenance of chromosomes 5)
Diseases named in the same sentence as SMC5 in open-access papers (continued):
Sharing a sentence is not in itself a finding about the gene and the disease.
persistent ductus arteriosus (1 paper, 2023). "SMC5 variants have been identified in patients with mild forms of CHD (persistent ductus arteriosus, arterial septal defect, or mild supravalvular pulmonic stenosis), all of which resolved without intervention." (PMID 38203602, 2023).
sarcoma (1 paper, 2020). A usually aggressive malignant neoplasm of the soft tissue or bone. "In our study, we found that SMC5 and SMC6 were both more highly expressed in sarcoma than in normal tissues, and also in human sarcoma cell lines." (PMID 33460400, 2020). "Our results also suggest that SMC1A and SMC2 are potential therapeutic targets for sarcoma, while levels of transcripts of SMC3, SMC4, SMC5 and SMC6 are potential prognostic markers to improve the survival rate and prognostic accuracy of sarcoma." (PMID 33460400, 2020). "According to the Cancer Cell Line Encyclopedia (CCLE), SMC1A, SMC2, SMC3, SMC4, SMC5 and SMC6 are also highly expressed in sarcoma cell lines." (PMID 33460400, 2020). "We concluded that SMC1A, SMC2, SMC3, SMC4, SMC5 and SMC6 were all highly expressed in sarcoma cell lines." (PMID 33460400, 2020). "GEPIA was used to investigate the prognostic ability of SMC1, SMC2, SMC3, SMC4, SMC5 and SMC6 expression in sarcoma." (PMID 33460400, 2020). "It was confirmed that the expression levels of SMC1A, SMC2, SMC3, SMC4, SMC5 and SMC6 in sarcoma were higher than in normal tissues." (PMID 33460400, 2020). "We found that increased expression of SMC1A, SMC2, SMC3, SMC4, SMC5 and SMC6 might play a significant role in sarcoma tumorigenesis." (PMID 33460400, 2020). "In contrast, SMC3, SMC4, SMC5, and SMC6 expression had no significant impact on OS or DFS in sarcoma." (PMID 33460400, 2020). "However, only the overexpression of SMC1A and SMC2 was related to the OS of sarcoma patients, whereas SMC3, SMC4, SMC5 and SMC6 had no significant impact on prognosis." (PMID 33460400, 2020).
synovial sarcoma (1 paper, 2020). "This revealed that SMC1A, SMC2, SMC3, SMC4, SMC5 and SMC6 proteins were all more highly expressed in the synovial sarcoma tissues than in corresponding normal tissues." (PMID 33460400, 2020).
cancer (23 papers, 2013 to 2026). A tumor composed of atypical neoplastic, often pleomorphic cells that invade other tissues. "We report a pan-cancer analysis of SMC5/6 variants across three databases in which thousands of tumors across all tissue types harbored copy number alteration (CNA) and/or small variants in SMC5/6 genes." (PMID 42181931, 2026). "By modeling SMC5/6 loss in cancer cell lines, we found that APOBEC3A activity elicited high levels of DNA breaks leading to genotoxic cell death." (PMID 38886582, 2024). "In this study, we find that deleterious mutations in SMC5/6 subunits correlate with high tumor mutational burdens in human cancers." (PMID 38886582, 2024). "Despite these data indicating an important role for the complex in genome integrity, SMC5/6 deficiency in human cancer is poorly understood." (PMID 38886582, 2024). "Somatic SMC5/6 mutations have been seen in many cancers, e.g., ovarian (20%), breast (18%), endometrial (14%), prostate (11%), and other cancer types." (PMID 39594644, 2024). "Previously it has been shown that Smc5/6 is recruited to ND10 associated with telomeres in ALT cancer cells." (PMID 28095508, 2017). "Mutations in human SMC5 have been associated with chromosomal instability and cancer." (PMID 40563397, 2025). "Given that mutations in various SMC-5/6 subunits are associated with genome instability disorders and cancer predisposition in humans, understanding the molecular pathology of the SMC-5(Y975D) complex can yield insight into how subtle perturbations in this complex can drive disease phenotypes." (PMID 40563397, 2025). "Mutations in the Smc5/6 complex have also been recently linked to cancer." (PMID 38847937, 2024). "Our results thus dissect Smc5/6 essential roles and reveal that combined defects in DNA damage tolerance and pausing site-replication cause recombination-mediated DNA lesions, which we propose to drive developmental and cancer-prone disorders." (PMID 26698660, 2015). "The unexpected synergy between caffeine and loss of SMC5/6 activity could potentially be exploited for new therapeutic strategies where one could preferentially sensitize checkpoint-compromised cancer cells to apoptosis." (PMID 23555814, 2013). "Our findings demonstrate that SMC5/6 complex disruption in cancer predicts elevated TMB and susceptibility to immunotherapy, indicating the potential to use SMC5/6 gene status for prognostic implications and tailored therapeutic approaches." (PMID 42181931, 2026). "Overall, these alleles represent powerful tools for future investigations into the multifaceted roles of the essential SMC-5/6 complex in maintaining genome stability, a process fundamental to preventing developmental diseases and cancer." (PMID 40563397, 2025). "To evaluate the interaction of APOBEC3A activity and SMC5/6 loss in human cancers, we quantified APOBEC3A mutational signatures in tumors with deleterious mutations in SMC5/6 subunit genes." (PMID 38886582, 2024). "Cancer cells depleted of SMC5/6 incur substantial genome damage from APOBEC3A activity during DNA replication." (PMID 38886582, 2024). "In cancer cells depleted of SMC5/6, deaminase-induced DNA damage was maximal during DNA replication." (PMID 38886582, 2024). "This study defines a novel role of the SMC5/6 complex in maintaining genomic stability and viability of cancer cells in which APOBEC3A is active, revealing a potential therapeutic vulnerability." (PMID 38886582, 2024). "Maintaining genome stability in the presence of active APOBEC3A involves SMC5/6-dependent stabilization of forks with single-strand gaps, suggesting a potential vulnerability of cancer cells." (PMID 38886582, 2024).
cancer (continued). "cBioPortal for Cancer Genomic database was also investigated and SMC5 showed a 3% and 2.6% alteration frequency, respectively, in COAD and READ." (PMID 35894836, 2023). "Our further analysis showed that lower expression of SMC5 had a poor prognosis in CRC patients, while improved SMC5 expression had a significant inhibitory effect on the cancer cell growth." (PMID 35894836, 2023). "In CRC patients of OXA_responders, SMC5 is expressed normally, the proliferation and migration of the cancer cells were decreased (Left)." (PMID 35894836, 2023). "Our study highlights SMC5/6 as an intrinsic immune sensor and restriction factor for a human herpesvirus RC and has implications for the pathogenesis of EBV-associated cancers." (PMID 35263599, 2022). "SMC5/6 complexes are essential for sumoylation of telomere-binding proteins to maintain telomere length in cancer cells utilizing alternative lengthening of telomeres (ALT)." (PMID 34944924, 2021). "A study using CRISPR to systematically perturb 222,784 gene pairs in two cancer cells lines determined a genetic interaction between SMC5 and a CSN component, COPS4, which resulted in a growth abnormality." (PMID 32384871, 2020). "Previous studies showed SMC5/6 also assists in the maintenance of telomere length in ALT cancer cells, whereby these cells acquire unlimited replicative potential." (PMID 33460400, 2020). "Another study reported that the Saos2 alternative lengthening of telomeres (ALT) cancer cell line requires SMC5/6 to promote telomere clustering and MiDAS at telomeres." (PMID 33200984, 2020). "Our findings in human cancers indicate a similar dependence of pol ε function on SMC5/6." (PMID 38886582, 2024). "Both mRNA and protein level of SMC5 was dramatically downregulated, which suggested that the downregulation of SMC5 might be benefit for the cancer cells and may therefore result in a poor prognosis of patients." (PMID 35894836, 2023). "Interestingly, SMC5/6 localizes at PML bodies in cancer cells (e.g. U2OS) that use the alternative lengthening of telomeres (ALT) mechanism to maintain their telomeres." (PMID 36373674, 2022). "Taking into account that the NSMCE2 subunit of the SMC5/6 complex has been shown to suppress cancer in mice, it is possible that the HBx mediated effects on ND10 and SMC5/6 could be important for HCC development." (PMID 34070716, 2021). "Interestingly, this complex has been shown to facilitate telomere homologous recombination and elongation in cancer cells, indicating that the SMC5/6 complex is required for telomere maintenance." (PMID 23805307, 2013). "Furthermore, while the expression of the TIMELESS/TIPIN complex limits telomeric MiDAS, the activity of the SMC5/6 complex encourages telomeric MiDAS, further supporting the role inhibition of SMC5/6 in the development of a therapeutic approach for ALT cancers." (PMID 37046606, 2023). "However, the upstream regulator of ATRX and SMC5 remains unclear, while our study provided the emerging evidence that U50A suppresses these genes to hinder cancer cell mitosis." (PMID 34944924, 2021). "However, the consequences of somatic SMC5/6 dysfunction in cancer are unknown." (PMID 42181931, 2026). "Further studies are needed to elucidate the relationships among MAGE proteins, Smc5/6 components, and proteins such as ATM and ATR that are also important for resistance to genotoxic agents in normal and cancer cells." (PMID 23555814, 2013). "In CRC patients of OXA_no‐responders, SMC5 is downregulated in the cancer cells, OXA treatment further decreased it resulting in extremely low SMC5 content, the proliferation and migration of the cancer cells were increased (Middle)." (PMID 35894836, 2023). "SLF2 has no known function in cancer yet has been identified as a DNA repair factor that acts as a localization factor of the SMC5/6 complex and other DNA damage and DNA repair factors at DNA damage sites." (PMID 37485814, 2023).
cancer (continued). "In contrast to the results presented here, a recent study using HCT116 cancer cells observed that the depletion of SMC5/6 complex components did not affect replication fork speed or CldU/IdU ratio." (PMID 33200984, 2020). "Meanwhile, our analysis verifies that SMC5 was downregulated upon OXA treatment, suggesting that for those patients with lower SMC5, OXA therapy may further reduce SMC5 level, which may further contribute to the malignant development of cancer cells." (PMID 35894836, 2023). "In CRC patients of OXA_no‐responders, SMC5 is downregulated in the cancer cells, the combination treatment of OXA and RTX could not decreased SMC5, the proliferation and migration of the cancer cells were decreased (Right)." (PMID 35894836, 2023).
infection (19 papers, 2015 to 2025). The state of being infected such as from the introduction of a foreign agent such as serum, vaccine, antigenic substance or organism. "Depletion of SMARCAD1 or SMC5 is associated with statistically significant increases in the number of viral genomes at 48 hpi in Ad5 WT infection compared to control siRNA treatment." (PMID 34463575, 2021). "Thus, it is only in the context of infection by an HBx-deficient HBV mutant that the antiviral activity of the SMC5/6 complex is revealed." (PMID 36862666, 2023). "HBV cccDNA is silenced naturally during infection by binding of the SMC5/6 complex to HBV cccDNA, and HBV antagonizes this silencing with the HBx protein that binds to SMC5/6 and triggers its proteasomal degradation." (PMID 38140556, 2023). "Since SMC5 is known to form a complex with SMC6, we also tested the impact of SMC5 depletion by siRNA on infection." (PMID 34463575, 2021). "During infection with human papillomavirus, SMC5/6 was found to localize to viral replication foci and depletion of SMC6 decreased total viral DNA levels." (PMID 34463575, 2021). "During Ad5 WT infection, depletion of SMARCAD1, SMC5, or SMC6 is associated with 2- to 3-fold, statistically significant increases in PFU at 24 hpi compared to control siRNA treatment." (PMID 34463575, 2021). "More recently, what appears to be its main role during infection was elucidated i.e., induction of Smc5/6 degradation." (PMID 29048354, 2017). "Firstly, it suggests that HBx does not strongly activate cellular transcription pathways in the context of natural infection, and instead supports the notion that Smc5/6 transcriptionally suppresses episomal (i.e. HBV cccDNA) but not genomic DNA." (PMID 28095508, 2017). "Collectively, these data indicate that Smc5/6 is an HBV restriction factor that is rapidly degraded upon infection through an HBx-dependent mechanism to allow viral gene expression and replication to occur." (PMID 29048354, 2017). "We also found that HBV infection and replication does not induce a prominent global host transcriptional response in PHH, either shortly after infection when Smc5/6 is present, or at later times post-infection when Smc5/6 has been degraded." (PMID 28095508, 2017). "It remains unclear whether the reduction of RCN2 represents an active viral mechanism, analogous to HBx-mediated degradation of the Smc5/6 complex, or a secondary consequence of infection-induced stress." (PMID 41201845, 2025). "Indeed, since the HBx protein is not present within the viral capsids, some basal level of HBx mRNA synthesis has to occur, early after infection, in order to induce Smc5/6 degradation and de-repress the HBV genome." (PMID 39405283, 2024). "As a result, loss of SMC5/6 expression, or inhibition of chromatin SUMOylation using the inhibitor TAK-981, rescues gene expression from unintegrated HIV-1 DNA and even allows IN− HIV-1 to establish a spreading infection in cultured T cells." (PMID 36376394, 2022). "As functions of the SMC5/6 complex are still emerging, comparative infections of cells with Ad5, HIV, HBV, and papillomavirus may be leveraged as virus models to explore the endogenous roles of SMC5/6." (PMID 34463575, 2021). "While this finding agrees with another reporting that HPV-5/-18 and BPV-1 E2 proteins do not influence the SMC6 abundance, it contrasts with studies of hepatitis B virus (HBV) wherein the master regulatory protein of HBV—HBx—was found to target SMC5/6 for degradation shortly after infection." (PMID 32992873, 2020). "To directly determine whether transcriptional silencing of cccDNA via Smc5/6 is associated with induction of innate immunity, we next studied the PHH response to infection with HBVΔX." (PMID 28095508, 2017). "It is tempting to hypothesize that HBV counters Smc5/6 repression of cccDNA transcription very early during infection by delivering HBx RNA into the cell." (PMID 28368357, 2017).
infection (continued). "Additionally, HBV RNA transcripts potentially could directly express HBx protein upon infection in a cccDNA-independent manner to support cccDNA transcription by antagonizing host restriction factors such as the SMC5/6 complex." (PMID 36519892, 2023). "Therefore, if Smc5/6 triggers an innate immune response after detecting cccDNA, activation of hepatocyte antiviral immunity would be expected to be limited to the first few days after infection prior to accumulation of HBx protein." (PMID 28095508, 2017). "Therefore, if Smc5/6 triggers an innate immune response in hepatocytes after detecting cccDNA, it is expected that there would be prolonged activation of antiviral immunity after HBVΔX infection." (PMID 28095508, 2017). "The data assessing the impact of depletion of SMARCAD1, SMC5, or SMC6 on Ad5 infection suggest that these proteins exert inhibitory effects on productive Ad5 infection, which are more pronounced during AdΔE4 infection." (PMID 34463575, 2021). "(A) Western blotting showing expression of SMC5, TRF1 and Actin (loading control) proteins in TRF1F/F MEFs after infection with GFP or CRE-Adenovirus and deletion of SMC5 by shRNA." (PMID 31934863, 2020). "Since Smc5/6 suppresses transcription of all detectable HBV RNAs, we next performed a series of infection studies with the same siRNAs in which we measured HBeAg levels as a surrogate of cccDNA transcriptional status." (PMID 28095508, 2017). "Furthermore, in our studies of HBV-ΔX infection of HepG2-NTCP cells with inducible HBx expression, preformed cccDNA can be recognized and directed to PML bodies in the presence of SMC5/6 and SLF2." (PMID 37338350, 2023). "Similarly, research on HBx showed that its target, the Smc5/6 complex, was also located in the ND10 bodies and was degraded early after infection." (PMID 36840581, 2023). "If loss of SMC5/6 complex function indeed inhibits the establishment of latent HIV-1 infections, then the FACS-sorted WT GFP− cells should contain more latent HIV-1 proviral DNA than the GFP− cells that lacked SMC5/6 function at the time of infection." (PMID 36376394, 2022). "During AdΔE4 infection, depletion of SMARCAD1, SMC5, or SMC6 is associated with no change in PFU at 24 hpi but is associated with 2- to 4-fold, statistically significant increases in PFU at 48 hpi compared to control siRNA treatment." (PMID 34463575, 2021). "Consistent with the statistical results, SMC5 did not significantly relocalize during AdΔE4 infection relative to mock or Ad5 WT infections." (PMID 34463575, 2021). "During AdΔE4 infection, depletion of SMARCAD1 is associated with no change in number of viral genomes, while depletion of either SMC5 or SMC6 is associated with statistically significant increases in viral genomes at 48 hpi compared to control siRNA treatment." (PMID 34463575, 2021). "In addition, we found that TRIM14 significantly inhibited the degradation of Smc5/6 by HBx, and this result was similar to that obtained with the HepG2-NTCP infection system." (PMID 30150992, 2018). "It has previously been shown that HBVΔX infection leads to establishment of cccDNA but not degradation of Smc5/6." (PMID 28095508, 2017). "We recently determined that Smc5/6 was degraded in the majority of HBV-infected human hepatocytes by the time cccDNA transcription could be detected, suggesting that HBx is expressed very early during infection." (PMID 28368357, 2017). "However, it is not yet clear how Smc5/6-mediated silencing is avoided in order to express HBx from newly synthesized cccDNA early after infection." (PMID 29048354, 2017). "Although the observed impacts of individual depletion of SMARCAD1, SMC5, or SMC6 were modest, this could be explained by redundancy within the host response since each of these proteins is part of families in which multiple members may be acting in a coordinated manner to inhibit infection." (PMID 34463575, 2021).
infection (continued). "During Ad5 WT or AdΔE4 infection, Ad5 hexon, penton, and fiber proteins show no meaningful change in abundance in the context of depletion of SMARCAD1, SMC5, or SMC6 compared to control siRNA treatment." (PMID 34463575, 2021). "It has previously been shown that infection of PHH by HBV, but not HBVΔX, leads to degradation of Smc5/6 and that knock-down of Smc6 rescues HBVΔX transcription." (PMID 28095508, 2017).